OGT (O-linked N-acetylglucosamine (GlcNAc) transferase)
Diseases named in the same sentence as OGT in open-access papers (continued):
Sharing a sentence is not in itself a finding about the gene and the disease.
pulmonary fibrosis (2 papers, 2023 to 2024). Chronic progressive interstitial lung disorder characterized by the replacement of the lung tissue by connective tissue, leading to progressive dyspnea, respiratory failure, or right heart failure. "In this study, we constructed a special Ogt knockout model to investigate the long‐term effect of OGT deficiency and found that Ogt knockout mice developed severe pulmonary fibrosis." (PMID 37963851, 2023). "Altogether, our data further confirms a mechanistic role for O-GlcNAc in the regulation of collagen in IPF and advocates for more research to explore OGT/O-GlcNAc as a modifiable target in slowing pulmonary fibrosis and fibrosis resolution." (PMID 38665916, 2024). "Since we observed increased O-GlcNAc in human and mouse pulmonary fibrosis and regulation of collagen expression by OGT in D. melanogaster, we wanted to determine the effects of reducing O-GlcNAc on fibrosis resolution." (PMID 38665916, 2024). "Unanswered questions remain, including the mechanism(s) whereby OGT/O-GlcNAc regulates collagen accumulation and degradation; which proteins involved in fibrosis are modified by O-GlcNAc, and whether OGT is a modifiable target in lung fibrosis." (PMID 38665916, 2024). "Aged mice (18 months), an established model for non-resolving pulmonary fibrosis, were administered 8 doses of OGT siRNA (siOGT), via oropharyngeal instillation, to knockdown OGT following peak fibrosis or 3 weeks post-bleomycin treatment." (PMID 38665916, 2024). "Collectively, these data demonstrate that the OGT/O-GlcNAc axis regulates collagen (and α-SMA) expression in vitro and may be a key mediator in the FMT, a process central to pulmonary fibrosis." (PMID 38665916, 2024). "Furthermore, we are the first to demonstrate that reducing O-GlcNAc, via oropharyngeal knockdown of OGT, resulted in resolution of fibrosis in a non-resolving murine model of pulmonary fibrosis." (PMID 38665916, 2024).
renal carcinoma (2 papers, 2022 to 2025). A carcinoma arising from the epithelium of the renal parenchyma or the renal pelvis. "Elevated O-GlcNAcylation and OGT expression act as oncogenic factors in renal cancer development, positioning OGT as a potential therapeutic target for renal cancer." (PMID 40852041, 2025). "The findings indicated that OGT overexpression might increase RCC cell proliferation by blocking apoptosis and accelerating the cell cycle, suggesting that O-GlcNAcylation and high OGT expression are oncogenic factors in the genesis of renal carcinoma." (PMID 36010674, 2022).
renal fibrosis (2 papers, 2024 to 2025). A final common manifestation of a wide variety of chronic kidney diseases characterized by glomerulosclerosis and tubulointerstitial fibrosis. "In HFD/STZ-induced DN rats, OGT inhibition with OSMI-1 significantly alleviated renal pathological damage, reduced ECM accumulation and inflammation, and prevented renal fibrosis and dysfunction." (PMID 41203135, 2025).
Sepsis (2 papers, 2024). Sepsis is defined as life-threatening organ dysfunction caused by a dysregulated host response to infection. "Conversely, myeloid cell-specific deletion of OGT in murine sepsis models precipitated heightened mortality and inflammation, implying a protective role for myeloid cell OGT in sepsis." (PMID 39493755, 2024). "Prior studies have shown that mice with a conditional knockout of OGT in macrophages, exhibit significantly increased RIPK3 activation, elevated synthesis of pro-inflammatory cytokines, and greater susceptibility to mortality in experimental sepsis compared to control mice." (PMID 39742284, 2024).
steatosis (2 papers, 2023 to 2025). Increased lipid within the cytoplasm of cells. "Mechanistic studies revealed that steatosis upregulated Host cell factor 1 (HCF1) and O‐GlcNAc transferase (OGT) expression, leading to catalyzed O‐GlcNAcylation at the T662 site of LIMA1 and subsequent inhibition of its ubiquitin‐dependent degradation." (PMID 39921472, 2025). "The study revealed that steatosis upregulated HCF1 and OGT expression, leading to catalyzed O‐GlcNAcylation of LIMA1 protein and subsequent inhibition of its ubiquitin‐dependent degradation." (PMID 39921472, 2025).
triple-negative breast carcinoma (2 papers, 2019 to 2023). An invasive breast carcinoma which is negative for expression of estrogen receptor (ER), progesterone receptor (PR), and human epidermal growth factor receptor 2 (HER2). "We find a greater dependency on OGT among triple-negative breast cancer (TNBC) cell lines, which respond to OGT inhibition by undergoing cell cycle arrest and apoptosis." (PMID 30952976, 2019). "Together, these data confirm the role of KLF8 and the KLF8/OGT loop in promoting stemness and chemoresistance of triple negative breast cancer cell, which may be used to develop strategy in BCSCs-specific treatment." (PMID 37152043, 2023).
uterine carcinoma (2 papers, 2024). A carcinoma involving a uterus. "We noted that the R17C mutation of OGT is involved in uterine carcinoma in TCGA, therefore we are interested in studying its underlying mechanism." (PMID 39276932, 2024). "The Cancer Genome Atlas (TCGA) reveals that the OGT-R17C mutation is implicated in uterine carcinoma." (PMID 39276932, 2024). "We set out from an R17C mutation of OGT, which is a uterine carcinoma mutation in The Cancer Genome Atlas." (PMID 39276932, 2024). "Moreover, we studied the R17C and S20A mutations in xenograft models and demonstrated that they both inhibit uterine carcinoma compared to wild-type OGT, probably due to less cellular reproduction." (PMID 39276932, 2024).
acute pancreatitis (1 paper, 2022). An acute inflammatory process that leads to necrosis of the pancreatic parenchyma. "Using a genetic model with haploinsufficiency of OGT, the enzyme responsible for O-GlcNAcylation, we observed the attenuation of the severity of acute pancreatitis induced by cerulein." (PMID 35336721, 2022).
adenoma (1 paper, 2024). A neoplasm arising from the epithelium. "In summary, our data suggest that upregulation of FASN during Apc-driven carcinogenesis increases the expression of GFPT1 and OGT and the level of O-linked glycosylation of proteins in intestinal and adenoma tissues." (PMID 38732103, 2024). "Western blot analysis on adenoma tissues confirmed that downregulation of FASN leads to a decrease in GFPT1 and OGT protein expression, with a more profound effect on expression of GFPT1." (PMID 38732103, 2024). "Immunohistochemistry analysis demonstrates that FASN, GFPT1 and OGT are highly expressed in mouse Apc/Cre intestinal adenomas as compared to surrounding normal mucosa and the patterns of FASN and GFPT1 expression are very similar in adenoma tissues." (PMID 38732103, 2024). "In summary, we show that an increase in FASN expression during adenoma formation and CRC progression leads to the upregulation of GFPT1 and OGT, as well as an increase in the level of O-GlcNAcylation and, consequently, to enhanced cellular proliferation, tumor growth and metastasis." (PMID 38732103, 2024).
adenovirus infection (1 paper, 2018). "Overexpression of OGT via adenovirus infection was also reported to increase O-GlcNAc levels and attenuate posthypoxic damage to cardiomyocytes." (PMID 30186544, 2018).
alcoholic steatohepatitis (1 paper, 2022). "It has been recently reported that RIPK3-controlled necroptosis is involved in the pathogenesis of alcoholic steatohepatitis and a spontaneous NASH-like syndrome due to loss of hepatic O-GlcNAc transferase (OGT)." (PMID 36107452, 2022).
Anxiety (1 paper, 2023). Intense feelings of nervousness, tension, or panic often arise in response to interpersonal stresses. "OGT in the placenta plays an important role in depressive and anxiety-like behaviors and memory impairment induced by prenatal stress and exhibits sex differences in offspring." (PMID 36757814, 2023).
Arthritis (1 paper, 2022). Inflammation of a joint. "However, the finding that targeted inactivation of OGT in monocytic cells also strongly ameliorates synovial inflammation highlights that monocyte-lineage cells are also targeted by the anti-inflammatory effects of O-GlcNAc in experimental arthritis." (PMID 35879285, 2022). "Targeted pharmaceutical or genetic inhibition of O-GlcNAc transferase (OGT) or O-GlcNAcase (OGA) arrests osteoclast differentiation during early stages of differentiation and during later maturation, respectively, and ameliorates bone loss in experimental arthritis." (PMID 35879285, 2022). "Potential effects on osteoblasts are thus insufficient to explain the findings obtained with OGT and OGA modulation in our arthritis models." (PMID 35879285, 2022).
Ataxia (1 paper, 2023). Ataxia refers to impaired coordination of voluntary muscle movement. "Furthermore, a loss of OGT in PCs induces severe ataxia, extensor rigidity and posture abnormalities in mice." (PMID 37107182, 2023).
brain injury (1 paper, 2017). Acute and chronic (see also brain INJURIES, CHRONIC) injuries to the brain, including the cerebral hemispheres, CEREBELLUM, and brain STEM. "Future studies using OGT KO mice restricted in glial cells, which are not currently available, will help reveal the role of glial OGT or glial O-GlcNAcylation in ischemic brain injury." (PMID 28878265, 2017).
breast ductal carcinomas (1 paper, 2016). "In breast ductal carcinomas, poorly differentiated tumors (grade II and III) displayed significantly higher OGT expression than grade I tumors." (PMID 27542217, 2016).
breast invasive carcinoma (1 paper, 2018). "Protein abundances of OGT and proteasome subunits are positively correlated in breast invasive carcinoma and colorectal adenocarcinoma." (PMID 29941490, 2018). "We analyzed proteomic data sets that were constructed from 102 breast invasive carcinoma cases and found positive correlations between OGT and the majority of proteasome subunits (left)." (PMID 29941490, 2018).
cervical adenocarcinoma (1 paper, 2015). An adenocarcinoma arising from the cervical epithelium. "Our results suggest that increased levels of MLL5 protein are correlated with upregulation of OGT and USP7 in primary cervical adenocarcinomas." (PMID 26678539, 2015). "Levels of MLL5, OGT and USP7 in 8 pairs of human cervical squamous cell carcinoma and 2 pairs of human cervical adenocarcinoma and adjacent normal tissues were analyzed via immunostaining with the appropriate antibodies." (PMID 26678539, 2015). "Here, we detected increased protein expression of OGT, USP7 and MLL5 in human primay cervical adenocarcinomas, compared with adjacent normal tissues." (PMID 26678539, 2015). "MLL5 protein levels were additionally correlated with increased OGT and USP7 expression in primary cervical adenocarcinomas." (PMID 26678539, 2015). "In addition, upregulation of MLL5 expression was correlated with increased expression of OGT and USP7 in human primary cervical adenocarcinomas." (PMID 26678539, 2015). "Notably, upregulation of MLL5 is correlated with increased expression of OGT and USP7 in human primary cervical adenocarcinomas." (PMID 26678539, 2015).
Chlamydia infection (1 paper, 2018). "We concluded that both OGT activity and vimentin glycosylation sites are required for IF reorganization during Chlamydia infection, and are co-opted by this pathogen to promote inclusion integrity and growth." (PMID 29513221, 2018).
chronic gastritis (1 paper, 2022). Inflammation of the stomach that is chronic in nature. "Tae and colleagues determined both O-GlcNAcylation and OGT expression in the epithelium and mononuclear inflammatory cells from biopsied tissues of chronic gastritis." (PMID 35432358, 2022).
cobalamin deficiency (1 paper, 2019). "Patients with N567K OGT variant did not suffer from cobalamin deficiency and expressed a much milder form of congenital anomalies than the severe HCF1 group, suggesting that a degree of HCF1 activity is retained." (PMID 31296563, 2019).
colonic adenomas (1 paper, 2014). "We observed that human colonic adenomas exhibit elevated O-GlcNAcylation, and increased levels of both OGT and OGA." (PMID 25000257, 2014). "This supports the immunoblotting data, which showed simultaneously increased OGT and OGA in colonic adenomas." (PMID 25000257, 2014).
colorectal adenocarcinoma (1 paper, 2018). The most common type of colorectal carcinoma. "In 62 cases of colorectal adenocarcinoma that expressed a detectable amount of OGT protein, positive correlation was obtained between OGT and almost all proteasome subunits that were examined (right)." (PMID 29941490, 2018).
Crohn disease (1 paper, 2022). A gastrointestinal disorder characterized by chronic inflammation involving all layers of the intestinal wall, noncaseating granulomas affecting the intestinal wall and regional lymph nodes, and transmural fibrosis. "These authors observed a decrease in O-GlcNAcylation and OGT expression levels in colon biopsies from patients with inflammatory bowel disease (Crohn's disease or ulcerative colitis), suggesting a protective role of OGT against inflammation in the gut." (PMID 36058931, 2022).
endothelial dysfunction (1 paper, 2025). In vascular diseases, endothelial dysfunction is a systemic pathological state of the endothelium (the inner lining of blood vessels) and can be broadly defined as an imbalance between vasodilating and vasoconstricting substances produced by (or acting on) the endothelium. "The most compelling finding of this study is the ability of OSMI-1, a selective OGT inhibitor, to reverse salt-induced endothelial dysfunction." (PMID 41476791, 2025). "The ability of OGT inhibition to reverse endothelial dysfunction highlights the therapeutic potential of targeting eNOS O-GlcNAc could be a promising approach for preventing salt-induced vascular damage and subsequent diastolic blood pressure elevation." (PMID 41476791, 2025). "Importantly, treatment with the OGT inhibitor OSMI-1 effectively reversed these molecular and functional alterations, suggesting that O-GlcNAc may serve as a critical and druggable target in high salt–induced endothelial dysfunction." (PMID 41476791, 2025).
epilepsy (1 paper, 2021). A brain disorder characterized by episodes of abnormally increased neuronal discharge resulting in transient episodes of sensory or motor neurological dysfunction, or psychic dysfunction. "Consistent with our results showing OGT-1 affects electroconvulsive seizure in our C. elegans model, epilepsy/seizures were identified in patients with missense mutations in OGT." (PMID 34797853, 2021).
facioscapulohumeral muscular dystrophy (1 paper, 2025). An autosomal dominant disorder affecting the skeletal muscles of the face, scapula, and upper arm. "Aberrations in Zscan4 have been linked to Facioscapulohumeral Muscular Dystrophy (FSHD) and we observed an increase in Zscan4 mRNA levels in OGT-CDG mESCs." (PMID 41033462, 2025).
fibrosarcoma (1 paper, 2022). A malignant mesenchymal fibroblastic neoplasm affecting the soft tissue and bone.
fibrosis (1 paper, 2024). the formation of excess fibrous connective tissue in an organ or tissue in a reparative or reactive process. "We were, however, able to reduce the increased OGT protein expression and O-GlcNAc levels to basal levels in a non-resolving fibrosis mouse model using oropharyngeal-delivered siRNA against OGT." (PMID 38665916, 2024).
gestational diabetes (1 paper, 2024). Carbohydrate intolerance first diagnosed during pregnancy. "In addition, OGT is selectively downregulated in male placentas from mothers with gestational diabetes, and mouse studies indicate that prenatal stress impacts OGT and O-GlcNAcylation levels more in males than in females." (PMID 38183126, 2024).
helminth infection (1 paper, 2022). "To verify that STAT6 acts downstream of OGT to control helminth infection-induced epithelial hyperplasia, we generated Ogti∆IEC-TgS6vt mice with concurrent STAT6vt overexpression and Ogt deletion in IECs." (PMID 36232438, 2022). "Our data clearly support our hypothesis that STAT6 mediates OGT’s function in regulating mucosal type 2 immune responses against helminth infection." (PMID 36232438, 2022).
Hepatic steatosis (1 paper, 2022). Steatosis is a term used to denote lipid accumulation within hepatocytes. "For example, OGT OE in the mouse liver only manifests as hepatic steatosis in the fed state while the lipolytic phenotypes of OGT KO in adipose or kidney proximal tube epithelial cells are stronger in fasted mice." (PMID 36111295, 2022).
Hyperammonemia (1 paper, 2022). An increased concentration of ammonia in the blood. "Glutamine and uridine are usually increased during hyperammonemia, and they are also required for the synthesis of UDP-GlcNAc, a high-energy sugar donor that is transferred onto Ser or Thr residues of intracellular target proteins by OGT." (PMID 36064721, 2022). "Moreover, liver OGT and OGA protein amounts were unchanged during hyperammonemia." (PMID 36064721, 2022).
Hypercalcemia (1 paper, 2021). An abnormally increased calcium concentration in the blood. "This study identifies a molecular mechanism of the O-linked N-acetylglucosamine transferase (OGT)-mediated enhancer of zeste homolog 2 (EZH2)/krüppel-like factor 2 (KLF2)/chemokine (C-X-C motif) ligand 1 (CXCL1) axis underlying the hypercalcemia-induced nerve injury in renal failure." (PMID 34462420, 2021). "Silencing OGT reduced the hypercalcemia-induced toxicity of neurons by inhibiting the expression of EZH2, which elevated the expression of CXCL1 in primary neurons by diminishing KLF2." (PMID 34462420, 2021). "Next, OGT silencing and CXCL1 overexpression were performed simultaneously in hypercalcemia-treated mouse neurons to further verify the effect of the OGT/EZH2/KLF2/CXCL1 axis on hypercalcemia-induced neurotoxicity." (PMID 34462420, 2021). "Initially, we found in this study that downregulation of OGT reduced the toxicity of primary neurons induced by hypercalcemia by inhibiting the expression of EZH2." (PMID 34462420, 2021). "Silencing OGT attenuated hypercalcemia-induced neurotoxicity by regulating the EZH2/KLF2/CXCL1 axis." (PMID 34462420, 2021). "In the current study, we explored the regulatory mechanism of OGT in hypercalcemia-induced nerve injury in renal failure and found that OGT promotes this injury by regulating the EZH2/KLF2/CXCL1 axis." (PMID 34462420, 2021). "In order to investigate the effect of OGT on hypercalcemia-induced nerve injury induced by renal failure and its molecular mechanism, we first constructed a CKD mouse model." (PMID 34462420, 2021). "In vivo experiments further confirmed that silencing OGT could reduce hypercalcemia-induced nerve injury in CKD mice." (PMID 34462420, 2021). "Then, OGT was silenced in primary neurons induced by hypercalcemia." (PMID 34462420, 2021). "Here, we further explore whether OGT can reduce hypercalcemia-induced neurotoxicity by silencing OGT." (PMID 34462420, 2021). "Hereby, it was inferred that OGT might mediate EZH2 in primary neurons induced by hypercalcemia." (PMID 34462420, 2021). "Taken together, silencing OGT downregulates EZH2, which increases the expression of KLF2 and then decreases the expression of CXCL1, thus alleviating hypercalcemia-induced nerve injury in renal failure." (PMID 34462420, 2021).